TXNIP (thioredoxin interacting protein)
Diseases named in the same sentence as TXNIP in open-access papers (continued):
Sharing a sentence is not in itself a finding about the gene and the disease.
asthma (6 papers, 2013 to 2024). "However, research examining the correlation between CuO NPs, asthma, and TXNIP is lacking, and there is a dearth of studies elucidating the role of TXNIP in the development and exacerbation of asthma caused by CuO NP exposure." (PMID 39518986, 2024). "Notably, our microarray association demonstrated decreased expression of TXNIP in asthma; this association has been independently validated in a comparison of active asthmatics vs. normal volunteers." (PMID 24188128, 2013). "In conclusion, our findings suggest that CuO NP exposure not only induces pulmonary toxicity but also exacerbates asthma, primarily through the activation of the TXNIP signaling pathway." (PMID 39518986, 2024). "In the present study, CuO NP exposure markedly induces pulmonary toxicity and exacerbates asthma by increasing inflammatory cell infiltration and inflammatory cytokine levels, accompanied by the activation of the TXNIP signaling pathway." (PMID 39518986, 2024). "This study aimed to investigate the pulmonary toxicity induced by CuO NPs and their impact on asthma, with a particular focus on the role of thioredoxin-interacting protein (TXNIP)." (PMID 39518986, 2024). "We showed that exposure to TiO2NPs aggravated asthma, increased TXNIP expression, and activated apoptosis in lungs of OVA-induced mice." (PMID 34576095, 2021). "In this study, we investigated the exacerbation of asthma in response to TiO2NP exposure in OVA-induced asthmatic mice and explored the underlying mechanisms involving TXNIP and apoptosis." (PMID 34576095, 2021). "For example, exposure to silica dioxide nanoparticles has been shown to worsen asthma and increase pulmonary toxicity via upregulation of TXNIP." (PMID 34576095, 2021). "Overall, TiO2NP exposure induced toxicological changes in the respiratory tract and exacerbated the development of asthma via activation of the TXNIP-apoptosis pathway." (PMID 34576095, 2021). "Another study indicated that silica nanoparticles aggravate airway inflammation and asthma development by increasing the protein expression levels of thioredoxin-interacting protein (TXNIP) and the NOD-like receptor pyrin domain-containing 3 (NLRP3) inflammasome." (PMID 35936002, 2022). "Moreover, we elucidated the aggravating effect of TiO2NP inhalation in respiratory tracts with asthma, along with the molecular pathogenesis through the regulation of TXNIP." (PMID 34576095, 2021). "Overall, exposure of TiO2NPs to mice increased the expression of TXNIP in lungs, demonstrating that TXNIP might be involved in the molecular pathogenesis of asthma." (PMID 34576095, 2021). "As mentioned, 4 of the developmental genes: LAMP1, PIP5K1B, SCARB2 and TXNIP, were differentially expressed in both asthma and upon stimulation of immortalized B-cells derived from asthmatics, suggesting a possible role of these genes in modulating the immune response in asthma." (PMID 24188128, 2013). "Finally, we noted that, of the 12 vitamin D lung developmental genes transcriptomically related to asthma susceptibility, 4 – LAMP1, PIP5K1B, SCARB2, and TXNIP – were significantly differentially expressed upon administration of vitamin D to cells derived from asthmatic children." (PMID 24188128, 2013). "Mice in the OVA group exhibited higher levels of TXNIP, p-ASK1, Bax, and cleaved caspase-3 expression compared with the NC group, and OVA-induced asthma mice exposed to CuO NPs indicated higher levels of expression than mice in the OVA group." (PMID 39518986, 2024). "Similarly, miR-20b targets the TXNIP, suppresses TXNIP expression, and reduces TXNIP binding to NLRP3, thereby limiting pyroptosis and airway inflammation in a murine model of asthma." (PMID 39131161, 2024). "Therefore, an in-depth study is needed to understand the apoptosis mechanisms triggered via TXNIP in OVA-induced mice and how TiO2NPs pathologically exacerbate the development of asthma." (PMID 34576095, 2021).
brain infarction (6 papers, 2016 to 2024). Tissue necrosis in any area of the brain, including the cerebral hemispheres, the cerebellum, and the brain stem. "Moreover, a knockout of TXNIP and pharmacological inhibition of TXNIP are reported to protect against brain infarction and neurological diseases in mouse models." (PMID 33803178, 2021). "Analyses revealed that Cel administration reduced brain infarction size, microglia activation, levels of inflammation factors, and levels of oxidative stress markers by upregulating levels of p-AMPKα, Nrf2, HO-1, and by downregulating levels of TXNIP and NLRP3." (PMID 38763946, 2024). "In addition, one study demonstrated that pharmacological inhibition by using resveratrol or genetic deletion of TXNIP attenuated brain infarction and neurological outcome in mice embolic mode via restoring redox-balance and inhibition of TXNIP-NLRP3 inflammasome activation." (PMID 27652274, 2016). "MiR-17-5p mimic administration ameliorated TXNIP expression, NLRP3 inflammasome activation, caspase-1 cleavage, and IL-1β production, as well as brain infarct volume." (PMID 29394934, 2018).
depression (6 papers, 2017 to 2025). "In this study, we firstly detected the influence of fluoxetine on astrocytic TXNIP level in depression, and observed that fluoxetine increased TXNIP-GLUT1 pathway-mediated glucose uptake in corticosterone-stimulated PFC astrocytes in vivo and in vitro." (PMID 36105196, 2022). "The signaling via NF-κB and thioredoxin-interacting protein (TXNIP) otherwise activates inflammasome, thus contributing to depression." (PMID 29351723, 2018). "Apart from that, TXNIP was also explored in mediating CUMS-induced depression by activating inflammasome." (PMID 29084550, 2017). "Thus, fluoxetine suppressed astrocytic TXNIP overexpression possibly via inhibiting GR nuclear translocation in corticosterone-induced depression." (PMID 36105196, 2022). "In a chronic mild stress (CMS) model of depression characterized by anhedonia, UCP2-deficient mice showed exacerbated depressive behaviors, whereas UCP2 overexpression produced antidepressant effects by suppressing the ROS-thioredoxin-interacting protein (TXNIP)–NLRP3 pathway in astrocytes." (PMID 41441267, 2025).
diabetic cardiomyopathy (6 papers, 2018 to 2024). Diabetic cardiomyopathy is a disorder of the heart muscle in people with diabetes. "Meanwhile, prior studies have identified that TXNIP is up-regulated in mice with diabetic cardiomyopathy, such that TXNIP knockdown averts the stimulating role of Ang II in cardiac fibrosis." (PMID 35148667, 2022). "Several studies have reported that TXNIP overexpression induces apoptosis in pancreatic β-cells and TXNIP-mediated cardiomyocyte apoptosis is highly involved in the pathogenesis of diabetic cardiomyopathy." (PMID 34358247, 2021).
hyperlipidemia (6 papers, 2019 to 2023). "A nonsense mutation in the TBP-2 gene was discovered in another study on HcB-19 mice, causing the mice to develop familial combined hyperlipidemia; thus, VDUP1/TBP-2 was called TXNIP." (PMID 37144033, 2023). "Taking these facts into account, damaged mitochondria are suspected to be the cause of LS and hyperlipidemia in the liver of TXNIP-KO mice during the fasted state." (PMID 35314758, 2022). "TXNIP-deficient mice show sensitivity to hyperlipidemia, and the TXNIP gene is located on the 1q21-1q23 chromosome within a T2DM locus." (PMID 31835423, 2019). "TXNIP gene deletion can lead to lethality under fasting conditions due to a switch in metabolism to hyperlipidemia and hypoglycemia." (PMID 33302545, 2020).
lymphoma (6 papers, 2016 to 2024). A malignant (clonal) proliferation of B- lymphocytes or T- lymphocytes which involves the lymph nodes, bone marrow and/or extranodal sites. "Indeed, treatment with 2-deoxyglucose (2DG) is a potent inducer of TXNIP and has been shown to be effective against lymphoma cells." (PMID 36761972, 2023). "Expression of the tumour suppresser gene TXNIP increased, while GPX1 and GPX4 expression, which are related to poor prognosis of lymphoma patients, decreased." (PMID 33451071, 2021). "Furthermore, the inter-dependent regulatory relationship between MondoA, TXNIP, and MYC has been seen in a variety of models, whilst the impact of NAC on MYC-dependent pathways has been seen in lymphoma." (PMID 39103698, 2024).
triple-negative breast carcinoma (6 papers, 2018 to 2023). An invasive breast carcinoma which is negative for expression of estrogen receptor (ER), progesterone receptor (PR), and human epidermal growth factor receptor 2 (HER2). "This is also consistent with another study in triple-negative breast cancer that TXNIP level is inversely correlated to MYC level, whereby MYC could repress expression of TXNIP." (PMID 29996811, 2018). "The poor survival of triple-negative breast cancer patients correlates with elevated c-MYC and decreased expression of TXNIP, which is probably due to c-MYC binding to the TXNIP promoter." (PMID 33228209, 2020).
allergic rhinitis (5 papers, 2021 to 2025). Inflammation of the nasal mucous membranes caused by an IgE-mediated response to external allergens. "The role of thioredoxin-interacting protein (TXNIP) is evaluated in oxidative stress in allergic rhinitis." (PMID 41154690, 2025). "Activation of nuclear factor kappa-light-chain-enhancer of activated B cells (NF-κB) and thioredoxin-interacting protein (TXNIP) are possible pathways of oxidative stress leading to inflammatory processes in allergic rhinitis." (PMID 39586518, 2025). "In the untreated allergic rhinitis group, nasal symptoms, TXNIP and OVA-specific IgE levels, histamine and cytokine levels, and MDA levels were increased, and SOD level was decreased, but these results were attenuated in the resveratrol-treated group." (PMID 34439514, 2021). "For allergic rhinitis, the role of thioredoxin-interacting protein (TXNIP) was evaluated in oxidative stress." (PMID 34439514, 2021). "The findings suggest that RESV may effectively alleviate allergic rhinitis by inhibiting the TXNIP‐mediated OS pathway." (PMID 38628180, 2024). "In addition, many studies have demonstrated the potential role of resveratrol in the treatment of allergic rhinitis, as it can effectively alleviate AR in mice by inhibiting the oxidative stress pathway of TXNIP, and its mediated activation of SIRT1 also attenuates ovalbumin-induced ARin mice." (PMID 41105646, 2025). "The study revealed significant changes in sneezing, nasal rubbing, inflammatory cytokine levels, eosinophil counts, TXNIP expression, and the levels of OS markers such as malondialdehyde and superoxide dismutase in RESV‐treated mice compared to untreated allergic rhinitis mice." (PMID 38628180, 2024).
brain injury (5 papers, 2017 to 2022). Acute and chronic (see also brain INJURIES, CHRONIC) injuries to the brain, including the cerebral hemispheres, CEREBELLUM, and brain STEM. "Therefore, we examined the contribution of ERS in TXNIP-Trx dysfunction utilizing SAL, which is a selective inhibitor of eIF2α and has been shown to exhibit anti-inflammatory effects in a rodent model of traumatic brain injury." (PMID 34276337, 2021). "However, no study has been reported on whether TXNIP is involved in septic brain injuries." (PMID 35571246, 2022).
fibrosis (5 papers, 2019 to 2025). the formation of excess fibrous connective tissue in an organ or tissue in a reparative or reactive process. "Correlation analysis also showed a significant association between increased TXNIP expression and the severity of fibrosis or ethanol intake in alcoholic patients with fibrosis." (PMID 38169654, 2024). "Finally, our results indicate that mRNA expression of TXNIP, a gene involved in oxidative stress and inflammation, was positively correlated with fibrosis risk, underscoring the role of oxidative stress in liver damage." (PMID 39941038, 2025). "Similarly, Masson trichrome staining indicated that NLRP3 deletion abrogated TXNIP overexpression‐induced worsening of cardiac fibrosis in obese hearts." (PMID 39604027, 2024). "However, little is known about the role of TXNIP and NLRP3 in post-MI fibrosis." (PMID 37850269, 2023).
Hepatitis (5 papers, 2020 to 2025). Inflammation of the liver. "Activation of p38 MAPK and ERK did not change in ethanol-fed TxnipΔEC mice, indicating that TXNIP protects against hepatic ALD by regulating JNK signaling." (PMID 38169654, 2024). "TXNIP was overexpressed mainly in LSECs, and mice genetically lacking Txnip in ECs exhibited accelerated liver injury, hepatitis, fibrosis, and HCC development following ethanol feeding." (PMID 38169654, 2024).
lung injury (5 papers, 2019 to 2022). "We found that activation of autophagy reduced TXNIP protein levels in the liver tissues of realgar-induced liver injury mice and weakened the interaction between TXNIP and NLRP3." (PMID 35628508, 2022). "RAGE, NLRP3 and TXNIP expressions were increased in an animal model of acute lung injury, a phenomenon that was reversed by RAGE inhibition." (PMID 36232959, 2022). "This further reveals the vital role of TXNIP playing in nerve injury." (PMID 34517790, 2021). "The roles of thioredoxin-interacting protein (TXNIP) and receptor for advanced glycation end-products (RAGE)-dependent mechanisms of NOD-like receptor family, pyrin domain containing 3 (NLRP3) inflammasome-driven macrophage activation during acute lung injury are underinvestigated." (PMID 36232959, 2022).
neuropathy (5 papers, 2019 to 2025). A disorder affecting the nervous system that manifests with pain, tingling, numbness, and/or muscle weakness. "Our results showed that TXNIP upregulation is associated with prediabetic neuropathy in HFD-fed mice." (PMID 30733849, 2019). "In this study, we provided the evidence that TXNIP upregulation is associated with the development of prediabetic neuropathy in the mice fed with an HFD." (PMID 30733849, 2019). "Previous studies have demonstrated that linarin prevents dry eye disease and neuropathy by inhibiting inflammation through the TXNIP/NLRP3 inflammasome pathway." (PMID 40265676, 2025). "Since TXNIP mediates inflammatory responses by binding the NLRP3 inflammasome, we also used intravitreal injection of MCC950, an NLRP3 inhibitor, to indirectly observe the relationship between TXNIP and neuropathy in glaucoma." (PMID 39736512, 2024). "TXNIP is significantly involved in the inflammation-related neuropathy of experimental glaucoma and probably facilitates M1-like microglial transformation via PI3K/Akt pathway." (PMID 39736512, 2024). "In pre-DM mice induced by high fat diet, the occurrence of neuropathy is related to the upregulation of TXNIP." (PMID 32774321, 2020). "The effects of mediating TXNIP on prediabetic neuropathy and its exact mechanism were performed using high-fat diet- (HFD-) induced diabetic mice and palmitate-treated neurons." (PMID 30733849, 2019). "In the present study, we confirmed through TXNIP knockdown that its upregulation contributed to the development of prediabetic neuropathy in the HFD-fed mice, as reflected by the increased MNCV and SNCV." (PMID 30733849, 2019). "Herein, we aim to investigate the role of TXNIP in prediabetic neuropathy and therapeutic potential of verapamil which has been shown to inhibit TXNIP expression." (PMID 30733849, 2019). "Moreover, we also focused on TXNIP function in the neuropathy process and found that deletion of TXNIP enhanced RGC survival and preserved retinal neuronal function in experimental glaucoma." (PMID 39736512, 2024). "Furthermore, we showed for the first time that verapamil as an inhibitor of TXNIP expression improved prediabetic neuropathy in the HFD-fed mice." (PMID 30733849, 2019). "Our results thus suggest that TXNIP might be a potential target for the treatment of prediabetic neuropathy." (PMID 30733849, 2019). "In addition, we also showed that verapamil, a known inhibitor of calcium channels, improved prediabetic neuropathy in the HFD-fed mice by inhibiting the upregulation of TXNIP." (PMID 30733849, 2019). "Thioredoxin-interacting protein (TXNIP) is involved in glucose and lipid metabolism, and associated with oxidative stress and inflammation, however, not known whether to be involved in glaucoma neuropathy and its underlying mechanisms." (PMID 39736512, 2024).
pancreatitis (5 papers, 2014 to 2024). Inflammation of the pancreas. "Studies have also found that, baicalein alleviates pyroptosis and inflammation in hyperlipidemic pancreatitis by inhibiting NLRP3/Caspase-1 pathway through the miR-192-5p/TXNIP axis." (PMID 36316322, 2022). "Interestingly, the phosphorylation of p38, JNK, and ASK1 diminished in TXNIP-KO mice with pancreatitis in comparison with wild-type mice." (PMID 36316322, 2022). "Furthermore, the potential mechanisms by which TXNIP can regulate pancreatitis through ASK1-JNK/p38 requires further study." (PMID 36316322, 2022). "Moreover, the development of cerulein-induced pancreatitis conspicuously stimulated the expression of TXNIP, the critical regulator of NLRP3 activity." (PMID 25214720, 2014). "The regulatory effects of S1P signaling on pancreatitis predominantly involve NF-κB, STAT3 phosphorylation, PERK/TXNIP/NLRP3, RhoA/ROCK, and AMPK/mTOR pathways as well as IFN-γ and TGF-β1." (PMID 39519028, 2024). "However, the specific role andmolecular mechanisms of TXNIP in the pathogenesis and progression of pancreatic cancercells have not been determined." (PMID 38229544, 2024).
prediabetes (5 papers, 2017 to 2025). "After stratifying byIRAK-M (<3.76 and ≥3.76 ng/mL), patients with a higher TXNIP level showeda greater risk of prediabetes or T2D in the subgroup with low IRAK-M(<3.76 ng/mL)." (PMID 36039603, 2022). "IRAK-M is independently and positively associated with prediabetes and T2D,while TXNIP is independently and negatively associated with prediabetes andT2D." (PMID 36039603, 2022). "In conclusion, our results provide evidence that IRAK-M is independently andpositively associated with prediabetes and T2D, while TXNIP is independently andnegatively associated with prediabetes and T2D." (PMID 36039603, 2022). "IRAK-M and TXNIP serve as diagnostic factors for prediabetes." (PMID 36039603, 2022). "In addition, subjects with higher TXNIP levels had ahigher risk of prediabetes and T2D (all p < 0.05)." (PMID 36039603, 2022). "Therefore, the combination of low IRAK-M andhigh TXNIP might be diagnostic for prediabetes." (PMID 36039603, 2022). "The highAUC values for IRAK-M (0.877) and TXNIP (0.872) in prediabetes and IRAK-M (0.983)and TXNIP (0.991) in T2D further suggested that IRAK-M and TXNIP are reliablemarkers of early T2D development." (PMID 36039603, 2022). "TXNIP was alsonegatively correlated with IRAK-M, suggesting that increased TXNIP is associatedwith prediabetes and T2D." (PMID 36039603, 2022). "TXNIP DNA methylation and gene expression in subjects with normal glucose tolerance compared to subjects with prediabetes." (PMID 29077742, 2017). "Moreover, the plasma level of TXNIP was significantlyhigher in patients with newly diagnosed prediabetes or T2D." (PMID 36039603, 2022). "IRAK-M and TXNIP showed high AUCvalues for patients with prediabetes." (PMID 36039603, 2022). "Furthermore, we performedROC curve analysis of IRAK-M or TXNIP for prediabetes and T2D." (PMID 36039603, 2022). "In addition,although TXNIP was suggested to be highly increased in patients with T2D, it isunclear whether TXNIP is increased in the prediabetes stages." (PMID 36039603, 2022). "Logistic regression analysisindicated that IRAK-M is an independent negative predictor of prediabetes and T2D,while TXNIP is an independent positive predictor of prediabetes and T2D." (PMID 36039603, 2022).